FH (fumarate hydratase)
Diseases named in the same sentence as FH in open-access papers (continued):
Sharing a sentence is not in itself a finding about the gene and the disease.
gastric cancer (4 papers, 2021 to 2024). A primary or metastatic malignant neoplasm involving the stomach. "A low s-FH-Ab level was an independent risk factor for poor prognosis and was associated with the malignant progression potential of gastric cancer." (PMID 38791507, 2024). "And gastric cancer patients with high FH expression had a higher risk of death than those with low FH expression." (PMID 34737838, 2021). "Assuming that s-FH-Ab reflects the amount of FH proteins, the emergence of s-FH-Abs in the early stages of gastric cancer may be caused by the excessive oxygen demand that occurs with tumor growth/spread." (PMID 38791507, 2024). "In this study, s-FH-Abs were overexpressed in the early stages of gastric cancer and gradually decreased with cancer progression." (PMID 38791507, 2024). "The s-FH-Ab levels were significantly higher in the gastric cancer group than in the control group (p = 0.01)." (PMID 38791507, 2024). "This study aimed to investigate the clinicopathological significance of fumarate hydratase (FH), a tricarboxylic acid cycle enzyme, in gastric cancer using autoantibodies as biomarkers." (PMID 38791507, 2024). "The Cancer Genome Atlas (TCGA) program dataset was referred to in order to show the FH-mRNA expressions in gastric cancer tissues and their impact on survivals." (PMID 38791507, 2024). "This study investigated the clinicopathological and prognostic significance of preoperative s-FH-Abs in gastric cancer." (PMID 38791507, 2024). "Studies have shown that FH expression in gastric cancer cells is significantly higher than that in nearby normal cells and is negatively correlated with patient prognosis." (PMID 36358574, 2022). "Because no study has analyzed autoantibodies against glycolytic enzymes or TCA cycle-related enzymes in solid tumors, this study aimed to investigate the clinicopathological and prognostic significance of serum FH antibodies (s-FH-Abs) in patients with gastric cancer." (PMID 38791507, 2024). "In addition, cisplatin is the first-line treatment for gastric cancer, and FH can significantly inhibit the cytotoxicity of cisplatin." (PMID 36358574, 2022). "Therefore, s-FH-Ab levels may be a useful biomarker for early diagnosis and the prediction of prognosis in patients with gastric cancer." (PMID 38791507, 2024). "s-FH-Ab levels were high in stage I gastric cancer but not in stages II–IV compared with those in the healthy control group." (PMID 38791507, 2024).
glomerulonephritis (4 papers, 2011 to 2022). A renal disorder characterized by damage in the glomeruli. "This N-terminal FH mutation manifested sequentially as glomerulonephritis (possibly C3G) and then aHUS in the same patient." (PMID 29321782, 2017). "Furthermore, fH-deficient mice rapidly developed severe LN-like glomerulonephritis by 12 weeks of life, with kidney biopsies demonstrating mesangial, endocapillary, and extracapillary proliferation and glomerular IC deposits, akin to LN in humans." (PMID 33562189, 2021). "Further research is needed to clarify whether the relationships between urinary fH and complement activation might recapitulate in other types of glomerulonephritis." (PMID 22111871, 2011).
hepatocellular carcinoma (4 papers, 2021 to 2023). A malignant tumor that arises from hepatocytes. "We found that after five days of CRISPR-Cas9 induction in HEK-293T cells (non-cancerous human embryonic kidney cell line) and one day with the HepG2 (hepatocellular carcinoma cell line), FH expression levels were almost completely abolished." (PMID 36428601, 2022). "We speculated that the binding sites of compound SIOC-XJC-SF02 against hepatocellular carcinoma cells may be fumarate hydratase (A0A0S2Z4C3)." (PMID 38139831, 2023).
hereditary cancer (4 papers, 2014 to 2023). Malignant neoplasms occurring in families at a rate greater than that expected by chance and caused by germline mutations in a specific gene. "Hereditary leiomyoma-renal cell carcinoma syndrome (HLRCC) is a hereditary cancer characterized by the inactivation of the Krebs cycle enzyme fumarate hydratase (FH)." (PMID 34502181, 2021). "Fumarate hydratase (FH) and succinate dehydrogenase (SDH) mutations were identified in several sporadic and hereditary cancers, causing accumulation of their substrates." (PMID 30356832, 2018).
leukemia (4 papers, 2017 to 2022). A malignant (clonal) hematologic disorder, involving hematopoietic stem cells and characterized by the presence of primitive or atypical myeloid or lymphoid cells in the bone marrow and the blood. "Furthermore, four genes that play a role in the citric acid cycle, namely IDH1, IDH2, SDH (succinate dehydrogenase) and FH (fumarate hydratase), are frequently mutated in leukemias and various types of solid cancers." (PMID 35386689, 2022). "Thus, loss of 5hmC expression is expected in tumours harbouring mutations in IDH, FH, SDH, similar to leukemias with mutations in TET2." (PMID 28484589, 2017). "Furthermore, it has been shown that while hematopoietic stem cells require fumarate hydratase (the enzyme that catalyzes this step) for self-renewal and maintenance, leukemia stem cells do not." (PMID 33777786, 2021).
oncocytic tumors (4 papers, 2021 to 2024). "Some oncocytic tumors are difficult to separate from papillary RCC, because oncocytic cytoplasmic changes can be seen in pRCC, translocation RCC and FH-deficient RCC." (PMID 34680535, 2021).
systemic lupus erythematosus (4 papers, 2021 to 2025). An autoimmune multi-organ disease typically associated with vasculopathy and autoantibody production. "FH suppression is observed in systemic lupus erythematosus (SLE) patient cells, suggesting its pathogenic role, indicating FH acts as a protective regulator, restraining mtRNA release to maintain appropriate cytokine and interferon responses and prevent aberrant immune activation." (PMID 41154608, 2025). "Knocking out fH in lupus-prone mice resulted in unrestricted alternative pathway activation, hypocomplementemia, accelerated kidney failure with marked albuminuria, and early mortality compared to lupus-prone mice with intact fH." (PMID 33562189, 2021).
tumor predisposition syndrome (4 papers, 2017 to 2026). "ULs can be associated with tumor predisposition syndromes, including HLRCC, Cowden syndrome, and Schwannomatosis, caused by germline mutations in FH, PTEN, and SMARCB1, respectively." (PMID 36773604, 2023). "Our patient did not have any symptoms suggestive of FH tumor predisposition syndrome, and her family history was negative for chordoma and FH-related complications." (PMID 38700789, 2024).
cyst (3 papers, 2013 to 2020). A sac-like closed membranous structure that may be empty or contain fluid or amorphous material. "We would suggest that the FH1 mouse model (both in vivo and in vitro) is a particularly valid model of the early stages of FH deficiency that lead as far as cyst development in vivo, and that factors yet to be defined may then act to drive cells toward neoplasia and further dysregulated metabolism." (PMID 23643539, 2013). "re-expression of extramitochondrial FH in mice with renal-specific FH1 deletion was sufficient to ameliorate cyst development and metabolic alterations in the urea cycle." (PMID 23643539, 2013).
dyslipidemia (3 papers, 2014 to 2023). "Several components of the alternative pathway (i.e., C3, C3a, FH, and properdin) as well as for one component of the classical pathway activation (C4) were significantly and positively associated with the metabolic syndrome." (PMID 30132263, 2018). "WES have advantages in diagnosing dyslipidemia in pediatric patients comparing with gene panels of FH." (PMID 36991406, 2023). "Also, we extend previous findings by reporting the associations of factor Bb, FD, FH, and properdin (components and regulators of the alternative pathway), with presence of the metabolic syndrome (significant only for FH and properdin)." (PMID 30132263, 2018). "This strongly suggests that, despite the observed strong cross-sectional associations, FH and properdin are not risk factors for the development of metabolic syndrome." (PMID 30132263, 2018). "In addition, the plasma concentrations of several complement factors (i.e., C3, C3a, FD, FH, properdin, C4) were higher in participants with the metabolic syndrome." (PMID 30132263, 2018). "This latter finding is particularly interesting given our current observation that C3, but not FH or properdin, was associated with the development of the metabolic syndrome." (PMID 30132263, 2018). "Second, we sequenced patient samples for the 23 dyslipidemia genes and 50 other related metabolic genes at a total cost of <$500.00 per sample, which was about half the cost of Sanger sequencing the three candidate FH genes only (∼$1,000.00 per sample)." (PMID 24503134, 2014). "We here show that at baseline, C3 and C4, but also systemic concentrations of C3a, FH, and properdin, were higher in individuals with metabolic syndrome compared to those without." (PMID 30132263, 2018).
hereditary tumor syndromes (3 papers, 2020 to 2026). "In addition to that, tumor progression is supported by a mutation in either succinate dehydrogenase complex (SDH) or fumarate hydratase (FH) enzymes which have antitumor effects in hereditary tumor syndromes." (PMID 37746258, 2023). "Due to the distinctive histomorphological appearance of the FH deficiency-driven neoplasms of uterus and kidney, pathologists play a central role in their initial recognition and hence identification of patients with increased risk for such hereditary tumor syndromes." (PMID 32612247, 2020).
hyperlipidemia (3 papers, 2021 to 2025). "In addition, hyperlipidemia was positively correlated with elevated levels of C3, C4, C1q, and FH proteins." (PMID 35370615, 2022).
Leydig cell tumor (3 papers, 2015 to 2021). A sex cord-stromal tumor occurring in the testis and rarely in the ovary. "Based on the study of other tumors, the authors concluded that some Leydig cell tumors are caused by germline FH mutations." (PMID 34200553, 2021). "Immunostaining for FH or 2SC was not performed in the previously reported cases, while in our patient, both the RCC and the Leydig cell tumor showed 2SC positivity, as expected in FH-deficient tumors." (PMID 31792767, 2020). "The three previously reported patients each had a different missense mutation in FH, and in contrast to the Leydig cell tumor of case 1, loss of the wild-type FH allele was demonstrated in the two testicular tumors." (PMID 31792767, 2020). "Leydig cell tumor/hyperplasia were also linked to many other situations than aneuploidies; these include: McCune-Albright syndrome, Carney complex, fumarate hydratase and cyclin dependent kinase (CDK) mutations." (PMID 26160035, 2015). "Whole exome sequencing (Illumina NovaSeq platform) was performed on the Leydig cell tumor, but a second hit in the FH gene was not identified." (PMID 31792767, 2020).
McCune-Albright syndrome (3 papers, 2015 to 2026). McCune-Albright syndrome (MAS) is classically defined by the clinical triad of fibrous dysplasia of bone (FD), cafe-au-lait skin spots, and precocious puberty (PP). "In addition to postzygotic somatic mosaicism of GNAS in McCune-Albright syndrome, rare examples of hereditary PBMAH have been described in the setting of APC-, MEN1-, FH-, PDE8B-, and PDE11A variant-driven pathogenesis." (PMID 29594118, 2018).
medullary carcinoma (3 papers, 2022). "Finally, a centralized pathological review was not performed, and CDC was easily misdiagnosed as others, such as medullary carcinoma and FH-deficient RCC, due to their similar microscopic features." (PMID 35879378, 2022). "Additionally, because pathological sections are not centrally re-confirmed by professional pathologists, CDC is easily misdiagnosed as others, including medullary carcinoma and FH-deficient RCC." (PMID 35530344, 2022).
metastatic disease (3 papers, 2023 to 2026). "While two patients had additional pathogenic VHL or FH variants, these have been described to have a lesser impact on metastatic disease." (PMID 39351526, 2024). "Patient 4 harbored a somatic FH pathogenic variant, which is often associated with metastatic disease." (PMID 39351526, 2024). "Nevertheless, the patient bearing the N154H mutation (PID332) demonstrated an aggressive metastatic tumor with strong 2SC and negative FH IHC staining, which confirmed FH loss in the tumor." (PMID 37053010, 2023). "However, since all patients with ATRX variants presented with aggressive/metastatic disease despite initially presenting with PCC (low metastatic risk) and VHL or FH variants (low-moderate metastatic risk), we speculate, as others, that ATRX variants contribute to metastatic risk." (PMID 39351526, 2024). "In our analyses of risk rate not adjusted for time, we found a significantly increased risk of metastatic disease in patients with pathogenic germline variants in SDHA, SDHB, SDHC, TMEM127, MAX, and FH compared to those with no identified pathogenic variant." (PMID 41183483, 2026).
neoplastic syndrome (3 papers, 2008 to 2013). A broad classification for disorders in which the development of neoplasms typically occur in association with a characteristic set of signs or symptoms. "This rare inherited tumour syndrome is caused by germ line mutations in the fumarate hydratase (FH) gene." (PMID 22799750, 2012).
skin cancer (3 papers, 2021 to 2025). "The evidence linking BRCA1/2, ATM, CHEK2, BRIP1, and FH pathogenic variants to increased skin cancer risk is limited." (PMID 41331641, 2025). "CLs in association with multiple ULs, in the absence of FH germline mutations, have been clinically observed, but their frequency and that of other skin tumours not investigated." (PMID 37606484, 2023). "Moreover, the microscopic features of FH non-mutated skin tumours were compared with those of an age-matched population group (n = 70) who presented, in their clinical history, only one type of skin tumour and no ULs." (PMID 37606484, 2023). "Although the patient had neither skin tumors nor a family history of HLRCC, an aggressive clinical course at her age and pathological diagnosis of FH-deficient RCC suggested a germline FH variant." (PMID 34360727, 2021).
Stroke (3 papers, 2015 to 2019). Sudden impairment of blood flow to a part of the brain due to occlusion or rupture of an artery to the brain. "Complement components that were significantly downregulated after stroke, C3b/ iC3b, C3, Factor H (fH) and Properdin, are more associated with the alternative pathway of complement activation." (PMID 31700615, 2019).
testicular cancer (3 papers, 2020 to 2023). A primary or metastatic malignant neoplasm that affects the testis. "Studies show that FH has been proposed to function as a tumor suppressor, as well as mutations, including missense, frameshift, nonsense, and large deletions exists in FH identified in the breast, bladder, and testicular cancer." (PMID 35006438, 2021).
acute kidney injury (2 papers, 2020 to 2021). Sudden and sustained deterioration of the kidney function characterized by decreased glomerular filtration rate, increased serum creatinine or oliguria. "In fact, the reduction of FH activity has been proposed as a biomarker of acute kidney injury." (PMID 34572472, 2021).
chondrosarcoma (2 papers, 2017). A malignant cartilaginous matrix-producing mesenchymal neoplasm arising from the bone and soft tissue. "As approximately 40% of the central chondrosarcomas lack detectable mutations in IDH, we investigated the possible involvement of two additional TCA cycle enzymes that are mutated in tumours, SDH and FH." (PMID 28484589, 2017).
dense deposit disease (2 papers, 2008 to 2015). "Pigs genetically deficient in fH and fH −/− mice spontaneously develop membranoproliferative glomerulonephritis type II." (PMID 18419792, 2008).
endometrial cancer (2 papers, 2024 to 2025). Primary or metastatic malignant neoplasm involving the endometrium (mucous membrane that lines the endometrial cavity). "When FH was overexpressed in endometrial cancer cells, the proliferative, migratory and invasive capacity of these cells was reduced, accompanied by partial inactivation of EGFR." (PMID 39403185, 2024). "FH knockdown leads to an increase in the phosphorylation level of epidermal growth factor receptor, thereby promoting the proliferation and metastasis of endometrial cancer." (PMID 41380966, 2025).
epilepsy (2 papers, 2016 to 2022). A brain disorder characterized by episodes of abnormally increased neuronal discharge resulting in transient episodes of sensory or motor neurological dysfunction, or psychic dysfunction. "However, previous studies evaluated the role of FH in other types of epilepsy." (PMID 27247579, 2016).
Hyperglycemia (2 papers, 2017 to 2022). An increased concentration of glucose in the blood. "Hyperglycemia was associated with lower levels of C1q, C3, and FH but higher serum levels of C3b." (PMID 35370615, 2022).
Infantile encephalopathy (2 papers, 2016 to 2020). Encephalopathy with onset in the infantile period. "For instance, PGK, NNT, SUCLA2, and FH have been linked to inherited disorders including, but not limited to, infantile encephalopathy, X-linked inherited disorders, myopathies, and neural tube defects." (PMID 33425810, 2020).
infertile (2 papers, 2023 to 2024). "Due to paucity of data, this study has provided initial insights on how heterozygous FH mutations are associated with infertility and therefore, how women seeking infertility treatment should be counselled." (PMID 37663422, 2023). "In this study, an infertile patient caused by FH gene mutation with HLRCC family history was successfully born with a healthy infant who blocked the family inheritance of the FH gene mutation through PGT-M selective embryo transfer after repeated tumor removal surgery and GnRH-a downregulation." (PMID 38933105, 2024). "Additional research is needed to investigate the impacts of FH mutations on infertility." (PMID 37663422, 2023). "The association between FH mutations and infertility remains uncertain." (PMID 37663422, 2023). "However, the cross-sectional nature of the study did not allow for a full investigation of the impact of FH mutations on infertility treatments and outcomes." (PMID 37663422, 2023). "Additional research with rigorous study designs and precise statistical analysis should be conducted to ascertain whether FH mutations with or without HLRCC increase the likelihood of infertility and which treatments result in higher success rates." (PMID 37663422, 2023).
intrahepatic cholangiocarcinoma (2 papers, 2025). A carcinoma that arises from the intrahepatic bile duct epithelium in any site of the intrahepatic biliary tree. "Univariate logit binomial analysis, with the outcome being the proliferative subclass status of intrahepatic cholangiocarcinoma, confirmed the significance of the probes for seven enzymes: FH, MAT2B, PLOD2, PLOD1, PDE6D, ALDOC, and NT5DC3." (PMID 40034261, 2025). "Based on the training and validation cohorts of intrahepatic cholangiocarcinoma (ICA) bulk transcriptomes, seven metabolic enzymes were confirmed to be overexpressed in cases with poor prognosis: FH, MAT2B, PLOD2, PLOD1, PDE6D, ALDOC, and NT5DC3." (PMID 40034261, 2025).
liver cancer (2 papers, 2022 to 2024). An epithelial or non-epithelial malignant neoplasm that arises from the liver. "By applying GSMMs, this study identified fumarate hydratase (FH) as a conserved gene for tumor growth in all liver cancer patients, whereas succinate dehydrogenase complex subunit A (SDHA) was predicted to be important for tumor growth in 60% of patients." (PMID 35121805, 2022).